PLXNB2 (plexin B2)
Diseases named in the same sentence as PLXNB2 in open-access papers (continued):
Sharing a sentence is not in itself a finding about the gene and the disease.
skin tumors (1 paper, 2021). "To assess the potential pathophysiological relevance of mechanosensation through Plexin-B1/Plexin-B2 in disease, we next analyzed the role of Plexin-B1/Plexin-B2 in skin tumors." (PMID 33637728, 2021).
thyroid cancer (1 paper, 2025). "Plasma proteomic studies have found that LCAT, GPX3, and leukotriene b4 can serve as potential biomarkers for thyroid cancer, and serum ISG15 and PLXNB2 can also serve as potential biomarkers." (PMID 40265010, 2025).
type 1 diabetes (1 paper, 2021). "This shape-based nature enabled us to discover multiple unique protein–phenotype links, including cathepsin H and type 1 diabetes (rs2289702 within CTSH), TREM-like transcript 2 protein and monocyte count (rs62396355 within TREML2) or plexin-B2 and systolic blood pressure (rs28379706 within PLXNB2)." (PMID 34819519, 2021).
tumor (37 papers, 2010 to 2025). "Global proteomic analysis reveals downstream effectors of the PLXNB2 pathway associated with tumor cell clustering." (PMID 40818975, 2025). "Interactions between plexin B2 and its canonical ligands, class IV semaphorins, have been implicated in promoting tumour invasion and metastasis by means of cytoskeletal remodelling and activation of RAC1 signalling." (PMID 39048831, 2024). "Surprisingly though, increased expression of PLXNA2 and PLXNB2 were primarily associated with increased cell resistance to a number of drug treatments, which seems to be contradictory to their primary roles as tumor suppressors." (PMID 32640719, 2020). "In addition, we performed qRT-PCR, IHC staining and Western blotting to analyse the expression of circPLXNB2, the PLXNB2 mRNA and protein, and proteins associated with cell cycle and apoptosis in mouse xenograft tumour tissues." (PMID 33757550, 2021). "According to this model, the inhibition of angiogenesis observed in Plexin-B2-depleted GBM xenografts in mice may be due to reduced tumor cell perivascular spread associated with the disruption of the Sema4C/Plexin-B2-mediated pro-migratory pathway." (PMID 31052281, 2019). "To determine the protein interactions between monocyte SEMA4A and tumor cell PLXNB2, we utilized the THP1 monocytic cells which express high SEMA4A ( > 80%) as an alternative source of human monocytes for heterotypic cluster formation." (PMID 40818975, 2025). "Conversely, cancer zone B utilized Sema4a/d-Plxnb2 and Pros1-Axl interactions to coordinate crosstalk within cancer_macro 1 populations, driving immune evasion and promoting tumor invasion and metastasis." (PMID 40723284, 2025). "Transcriptome analysis showed upregulation of brain‐derived neurotrophic factor (BDNF), semaphorin 7A (SEMA7A), and plexin‐B2 (PLXNB2) in SUDHL6‐EBV derived tumor tissues." (PMID 40488319, 2025). "This interaction is significant because it suggests that PLXNB2 not only plays a role in tumor cell behavior but also influences immune cell recruitment and adhesion, which can impact the tumor microenvironment and metastatic niche." (PMID 40818975, 2025). "Given that tumor cell clusters are powerful precursors to metastatic colonization, we wanted to determine if PLXNB2 levels would impact tumor cell seeding to the lungs." (PMID 40818975, 2025). "Meanwhile, the presence of THP1 monocytes promoted the metastatic colonization of both WT and PB2 KO tumor cells within 4 days, possibly through both PLXNB2-dependent clustering and clustering-independent factors, such as stemness." (PMID 40818975, 2025). "The mouse lungs, however, showed a significant 23-fold reduction of the metastatic burden from PLXNB2 KO tumors compared to those of control tumors, which were normalized by tumor weight." (PMID 40818975, 2025). "Interactions of PLXNB2 with its ligands SEMA4C on tumor cells and SEMA4A on myeloid cells (monocytes) promote homotypic and heterotypic CTC cluster formation, respectively, thereby driving lung metastasis." (PMID 40818975, 2025). "To reveal the transcription factors mediating the effects of plexin B2 in metastases, we used the chromatin profile of tumour cells to identify differentially accessible peaks and their associated motifs." (PMID 39048831, 2024). "We dissect a mechanism through which plexin B2 interacts with class IV semaphorins on tumour cells, leading to KLF4 upregulation and thereby promoting the acquisition of epithelial traits." (PMID 39048831, 2024). "Interactions between plexin B2 on hepatocytes and sempahorins on disseminated tumour cells regulate metastatic seeding in the liver." (PMID 39048831, 2024). "Circ_0013958 prevents plexin-B2 downregulation by miR-637 and, as a result, promotes cell proliferation, migration, invasion, and tumor growth." (PMID 37627074, 2023). "PLXNB2 can also finetune the invasive growth process under both physiological conditions and tumor growth and metastasis." (PMID 35335125, 2022).
tumor (continued). "Overall, Plexin-B2 was present in 100% RMS cells in human tumor samples at low intensity in aRMS and at intermediate to high intensity in eRMS." (PMID 35570846, 2022). "Consistently, IF for human integrin β1 outlined the orientation of the migrating GBM cells at the tumor border in close alignment with blood vessel axes in the Plexin-B2 KO transplants, in contrast to the alignment with striatal axon bundles in controls." (PMID 33514835, 2021). "Deletion of Plexin-B2 in GBM stem cells limited tumor spread and shifted invasion paths from axon fiber tracts to perivascular routes." (PMID 33514835, 2021). "SD2 transplants expanded slower than SD3, but both exhibited wide dissemination; notably, Plexin-B2 KO limited tumor spread in both SD2 and SD3 transplants." (PMID 33514835, 2021). "The in vivo Plexin-B2 KO phenotypes of tumor cell migration streams suggested increased intercellular adhesiveness." (PMID 33514835, 2021). "We next tested tumor invasion of transplanted GSCs with forced overexpression (OE) of Plexin-B2, and WB indicated that Plexin-B2 levels reached ~1.7- to 2.4-fold in OE cells relative to that in control)." (PMID 33514835, 2021). "In cancer plexins can be either oncogenic or tumor suppressors; for example, plexins A1-4 are tumor suppressors while plexin-B2 is tumor promoting and plexin D1 has been associated with tumor vasculature." (PMID 32117864, 2020). "Remarkably, immunostaining for the endothelial marker CD31 revealed a marked reduction in tumor vascularization in Plexin-B2 knockdown tumors." (PMID 25762646, 2015). "The PB2 WT cells formed larger and more heterotypic clusters with WBCs than PB2 KO cells without affecting tumor cell viability, demonstrating that PLXNB2 promotes heterotypic tumor-WBC cluster formation in which tumor cells can possibly evade immune cell killing." (PMID 40818975, 2025). "The Plxnb2, which is a receptor for Sema4d, showed the highest expression in tumor epithelial cells, suggesting that the elevated levels of Sema4d in Mir34aΔMye CACs might have an impact on tumor cells towards increased invasiveness." (PMID 39425000, 2025). "SEMA4C KD alone mimicked PB2 KO in reducing the average size and numbers of WT tumor cell clusters, whereas loss of both PLXNB2 and SEMA4C together did not have an additional impact on cluster size compared to PB2 KO alone." (PMID 40818975, 2025). "To determine the importance of PLXNB2 in tumor-monocyte clustering, we found that in mixed cell suspension, PLXNB2 control tumor cells formed clusters effectively with THP1 cells (1:4 ratio), whereas PB2 KO TNBC cells lost the capability for heterotypic cluster formation." (PMID 40818975, 2025). "Understanding the dual role of PLXNB2 in both tumor cell adhesion and immune cell dynamics could offer new therapeutic strategies aimed at disrupting these processes to reduce metastasis and improve patient outcomes." (PMID 40818975, 2025). "Based on our CellSearch data that demonstrated PLXNB2 enrichment in the CTC-WBC heterotypic clusters, we hypothesized that PLXNB2 in tumor cells impacts interactions with immune cells." (PMID 40818975, 2025). "Groups C and F, with clustering-specific up-regulation and down-regulation in protein expression, respectively, identified pathways in protein folding and hydroxylation, UV protection, and response to gamma radiation, all of which were over 10-fold enriched in PLXNB2+ tumor cell clusters." (PMID 40818975, 2025). "Considering the tumor-myeloid interactions promoted by PLXNB2, PLXNB2 may also promote intravasation of tumor cells in addition to CTC dissemination." (PMID 40818975, 2025). "Similarly, after 4 h pre-clustering with unlabeled THP1 monocytes, heterotypic L2G+ tumor cell-THP1 clusters promoted tumor cell dissemination (12 h), in a PLXNB2-dependent manner." (PMID 40818975, 2025). "We hypothesized that SEMA4C is a primary ligand of PLXNB2 in driving homotypic tumor cell clusters in metastasis." (PMID 40818975, 2025).
tumor (continued). "Moreover, expression of Klf4 as well as its predicted target genes was increased in tumour cells in Plxnb2-OE livers, as well as in AKPS organoids treated with rmPlexin B2." (PMID 39048831, 2024). "The results presented here identify the interaction between hepatocyte-derived plexin B2 and class IV semaphorins on tumour cells as a necessary inducer of KLF4-mediated epithelialization of liver metastases and lay a methodological framework to deepen our understanding of metastatic seeding." (PMID 39048831, 2024). "Notably, 86% of the Plxnb2-OE mice developed spontaneous liver metastases 8 weeks after orthotopic tumour inoculation (AKPS organoids), while only 29% of control littermates did." (PMID 39048831, 2024). "Additionally, plexin-B1 and plexin-B2 were also found to function as tumor suppressors in basal cell carcinoma." (PMID 37627074, 2023). "In stem cells from cancers of unknown primary tumors, plexin-B2 that was mutated in its extracellular IPT domain (G842C) is constitutively active, promoting their ability to proliferate and their tumor-forming ability." (PMID 37627074, 2023). "Given the data on the critical role of CD100 in DETC function, it is possible that plexin B2 may function as a tumor stress signal that is important for γδ T cell tumor immunosurveillance and promotion of antitumor immunity." (PMID 35480230, 2022). "Notably, CF-1, a PDX explant primary tumor cell culture, showed the highest Plexin-B2 expression and RD (eRMS) showed the lowest Plexin-B2 expression compared to all the RMS cell lines." (PMID 35570846, 2022). "At present, high PLXNB2 expression has been confirmed in various malignant tumours, including malignant glioma, ovarian cancer and breast cancer, and is closely related to the proliferation, invasion and poor prognosis of tumours." (PMID 33757550, 2021). "Moreover, circ_0013958 silencing enhanced the level of miR-637 and decreased the mRNA and protein levels of PLXNB2 in xenograft tumor tissues, thereby curbing the growth of OC tumor in vivo." (PMID 34367233, 2021). "While in the control transplants, invading tumor cells displayed a preference for axon fiber tracts, they displayed an increased preference for migration along microvasculature in Plexin-B2 KO cohort, with nuclear orientation in alignment with blood vessel axes." (PMID 33514835, 2021). "Importantly, circPLXNB2 accelerated tumour growth and progression, possibly by regulating PLXNB2 expression." (PMID 33757550, 2021). "Future studies will also be needed to explore whether Plexin-B2 manipulation in GBM cells affects tumor vascularization patterns." (PMID 33514835, 2021). "Importantly, we found that ANG and PLXNB2 knockdown resulted in a faster exhaustion of the in vivo tumor-initiating ability of CSCs as assessed by the relative tumor growth rate between passages one and three." (PMID 31942000, 2020). "Tumors derived from ANG and PLXNB2 knockdown CSCs were larger than those derived from the same number of control shRNA-transfected CSCs, accompanied with an increase in Ki-67 positive cells in the tumor sections." (PMID 31942000, 2020). "Interestingly, Plexin-B2 knockdown in intracranial U87MG transplants also resulted in markedly reduced tumor vascularization." (PMID 31052281, 2019). "From the mass spectrometry analyses, the unexpected identification of the tumor cell PLXNB2 signaling pathway in connection with astrocyte activation and immune response might imply its role in regulating the immune microenvironment of central nervous system (CNS) and other organs." (PMID 40818975, 2025). "Interestingly, loss of SEMA4A alone in monocytes was sufficient to reduce the size of heterotypic PLXNB2+ tumor clusters which is comparable with the effects of PB2 KO in tumor cells, suggesting that SEMA4A is the primary ligand on monocytes for PLXNB2-dependent tumor-monocyte clustering." (PMID 40818975, 2025).
tumor (continued). "Next, to determine whether the G842C mutation can actually drive tumor cell proliferation, we overexpressed wild‐type or mutated PlxnB2 in AS901, AS906, and AS67, which do not basally carry the mutation (validation data in Fig EV3)." (PMID 36722641, 2023). "Finally, to determine the role of mouse Plxnb2 in CTC-immune cell cluster formation, we knocked down Plxnb2 gene expression in mouse 4T1 TNBC cells with siPlxnb2 transfections and found that loss of Plexin-B2 in tumor cells diminished the heterotypic 4T1-mouse WBC cluster formation." (PMID 40818975, 2025). "Plexin-B2 was found to mediate ANG stimulation of rRNA transcription, ANG-induced phosphorylation of AKT and ERK, and the resulting proliferation of tumor cells." (PMID 37627074, 2023). "Among the identified interactions, we suggest EDN1/EDNRB as a putative novel tumor/endothelial cell interaction, and ANG/PLXNB2 and ANG/EGFR as putative new autocrine loops in ccRCC cancer cells." (PMID 38025776, 2023). "IHC scores of Plexin-B2, SEMA4C, SEMA4D, and SEMA4 were calculated based on the percentage of stain present and the stain intensity of tumor cells in the tumor tissues of human patients and mouse models." (PMID 35570846, 2022). "PLXNB2 is the functional cell surface receptor of ANG, which was originally identified as a tumor angiogenic factor." (PMID 35335125, 2022). "SEMA4D (CD100) binds 3 types of receptors, Plexin-B1 (PLXNB1), Plexin-B2 (PLXNB2), and CD72, which are all expressed by APCs (B cells, monocytes, DCs), endothelial cells, and tumor cells." (PMID 33741032, 2021). "On a cellular level, Plexin-B2 adjusts cell adhesiveness, migratory responses to different matrix stiffness, and actomyosin dynamics, thus empowering GBM cells to leave stiff tumor bulk and infiltrate softer brain parenchyma." (PMID 33514835, 2021). "First, we demonstrated that Plexin-B2 lowers cellular adhesion, a critical step for GBM cells to detach from tumor bulk and initiate invasion." (PMID 33514835, 2021). "SEMA4D binds three types of receptors, Plexin-B1 (PLXNB1), Plexin-B2 (PLXNB2), and CD72, which are all expressed by APCs, endothelial cells, and tumor cells." (PMID 34948104, 2021). "In Plexin-B2 knockdown U87MG transplants, tumor areas were largely devoid of CD31+ microvessels and the overall tumor volumes were markedly reduced." (PMID 25762646, 2015). "PLXNB2 is identified as a driver that promotes both homotypic and heterotypic CTC clustering through its interactions with Semaphorin ligands SEMA4C on tumor cells and SEMA4A on monocytes, in addition to PLXNB2 functions in proliferation and other known functions." (PMID 40818975, 2025). "After orthotopically implanting 10,000 tumor cells into the fourth mammary fat pads of NSG mice to ensure tumor growth of both L2G-labeled WT (pool control clonalities) and PLXNB2 KO MDA-MB-231 cells (pooled KO cells), we assessed spontaneous metastasis of these tumors to the lungs." (PMID 40818975, 2025). "Using human tumor cell-THP1 clusters at an optimized 1:4 ratio and anti-PLXNB2 antibody for co-immunoprecipitation, we also detected the enrichment of SEMA4A and CDC42 in the PLXNB2 protein complex, compared to monocytes only." (PMID 40818975, 2025). "Recent in vivo interaction screening studies have demonstrated that plexin B2 expressed by hepatocytes interacts with class IV semaphorins on tumor cells, leading to the upregulation of KLF4, which subsequently promote MET and facilitates tumor metastasis." (PMID 41415713, 2025). "Cumulatively, these data support the role of plexin B2–semaphorin–KLF4 signalling in promoting liver seeding, and might explain the differential ability of distinct tumour cell subpopulations to successfully form hepatic metastases." (PMID 39048831, 2024).
tumor (continued). "In summary, our studies highlight the complexity of tumor invasion and the importance of physical interactions of invading GBM cells with the environment that are dictated by the biomechanical properties controlled by proper levels of Plexin-B2 activity." (PMID 33514835, 2021). "Interestingly, Plexin-B2 OE also reduced GBM spread, with tumor cells remained congregated at the engraftment site, suggesting that a fine-tuned and balanced Plexin-B2 activity is required for successful GBM invasion." (PMID 33514835, 2021). "Combinatorial therapy of docetaxel (DTX) and a PLXNB2 mAb inhibited chemo-resistant CSC tumors and delayed disease recurrence, suggesting that targeting ANG/PLXNB2 is an effective means for eliminating quiescent CSCs in tumor therapy." (PMID 31942000, 2020). "The mammosphere phenotype in PB2 KO cells was restored by overexpression of the full-length PLXNB2 and to a lesser extent by overexpressed dECTO PB2 mutant, suggesting that the extracellular domain of PLXNB2 is necessary for its functions in promoting self-renewal of tumor cells." (PMID 40818975, 2025). "These PLXNB2 KO cells did not significantly alter cellular growth (confluence), viability, cell migration, and invasion in vitro as well as 10,000 tumor cell-mediated growth curves in vivo whereas the tumorigenesis in serial dilutions of 10 to 1000 cell implants was compromised." (PMID 40818975, 2025). "Moreover, addition of recombinant mouse plexin B2 ectodomain (rmPlexin B2) on AKPS single cells significantly increased CFUs both in the presence and absence of hepatocytes, suggesting that plexin B2 directly binds to tumour cells." (PMID 39048831, 2024). "In addition, NRP1, PLXNB2, and PLXND1 also showed increased expression in immune subtype C3, which is correlated with better prognosis, indicating these genes may also play tumor suppressor roles in certain conditions." (PMID 32640719, 2020). "Furthermore, our studies reveal proteins such as MCM7 as downstream mediators of the PLXNB2 interaction network that are required for PLXNB2-mediated tumor cluster formation but might not be sufficient to rescue surface protein-mediated intercellular crosstalk." (PMID 40818975, 2025). "SEMA4A+ monocytes with PLXNB2+ tumor cells (double positive) formed the largest clusters with more cell counts per cluster and in highest numbers of clusters compared to single-negative or double-negative combinations of SEMA4A−/+ monocytes with PLXNB2+/− tumor cells in heterotypic clustering." (PMID 40818975, 2025).